OGT (O-linked N-acetylglucosamine (GlcNAc) transferase)
Diseases named in the same sentence as OGT in open-access papers (continued):
Sharing a sentence is not in itself a finding about the gene and the disease.
heart failure (11 papers, 2016 to 2025). Inability of the heart to pump blood at an adequate rate to meet tissue metabolic requirements. "OGT adds O-linked β-N-acetylglucosamine to the serine/threonine residues of proteins and is upregulated during cardiac hypertrophy and subsequent heart failure." (PMID 39451203, 2024). "Consistent with a protective role of O-GlcNAcylation, loss of cardiomyocyte OGT leads to detrimental cardiac remodeling and heart failure following acute MI." (PMID 36359905, 2022). "Indeed, the long-term infusion of ISRIB demonstrated a significant effect in delaying the progression of heart failure in OGT-deficient mice, linking O-GlcNAcylation and the ISR in an in vivo model of cardiac pathophysiology." (PMID 41101503, 2025). "In addition, constitutive deletion of cardiomyocyte OGT causes partial perinatal lethality, and surviving knockout mice showed heart failure with more fibrosis, apoptotic cells and hypertrophy." (PMID 32251422, 2020). "Thus, loss of OGT or loss of OGA create the same result in chronic conditions (at least in heart failure) because both interventions block cycling of O-GlcNAc, despite having opposing effects on steady state O-GlcNAc levels." (PMID 33253217, 2020). "In summary, the genetic approach employed here efficiently depletes OGT and O-GlcNAcylation in the adult heart, that is characterized by the upregulation of molecular markers of heart failure but also expression levels of eIF2α and GCN2." (PMID 41101503, 2025). "This suggests that OGT is involved not only in cardiac hypertrophy but also in fibrosis and heart failure progression." (PMID 39451203, 2024). "There, we found that the induction of OGT was likely a pro-adaptive response in the heart to attenuate the severity of heart failure." (PMID 33253217, 2020). "In other words, suppression of OGT (and, by extension, decreasing O-GlcNAcylation) exacerbates heart failure." (PMID 33253217, 2020). "That is, in our previous investigation of OGT deletion in heart failure, we found that the mice did worse—similar to the present observations." (PMID 33253217, 2020). "To this end, we have previously investigated the role of OGT in a murine model of infarct-induced heart failure." (PMID 33253217, 2020). "More specifically, cardiac-specific OGT overexpression resulted in an approximate 6-fold increase in protein O-GlcNAcylation and heart failure, whereas dnOGAh mice exhibit more modest increase in O-GlcNAcylation (<2-fold) and diastolic dysfunction (without impact on systolic parameters)." (PMID 40747493, 2025). "Similarly, investigations in animal models with acute MI and heart failure found increased cardiac O-GlcNAcylation, accompanied by increased OGT and decreased OGA abundance or activities." (PMID 36359905, 2022). "Owing to this, increased O-GlcNAcylation and OGT expression during heart failure in mice are observed, suggesting that protein O-GlcNAcylation as vital compensatory mechanism may be required for pressure overload hypertrophy and infarct-induced heart failure." (PMID 30082668, 2018). "Moreover, the ablation of OGT from cardiomyocytes is involved in the induction of heart failure; indeed, OGT is an important part of the endogenous compensatory response to infarct-induced heart failure." (PMID 31059534, 2019). "While OGT and OGA activity have not been examined during heart failure, in models such as IPC and rIPC, elevated O-GlcNAcylation (50%) is associated with increased OGT abundance (100%) and activity (100–300%)." (PMID 37949223, 2023). "Deletion of OGT in adult mouse heart accelerates the progression of ischemia-induced heart failure without affecting cardiomyocyte size." (PMID 32251422, 2020).
ovarian carcinoma (11 papers, 2019 to 2024). A malignant neoplasm originating from the surface ovarian epithelium. "GO analysis of OGT/OGA associated genes with ovarian cancer." (PMID 35795059, 2022). "More importantly, we found the aberrant expression of OGT was significantly correlated with the pathological stage in ovarian cancer patients, while changes in OGA seems only have limited impact." (PMID 35795059, 2022). "In A2780 and SKOV3 ovarian cancer cells, down-regulation of OGT reduces O-GlcNAcylation of SNAP-23 promoting the formation of SNARE complex and exosomes." (PMID 36059648, 2022). "HBP- and OGT-inhibitors promote resistance of ovarian cancer cells to platinum-based chemotherapy by inducing autophagy and secretion of exosomes that decrease intracellular drug levels." (PMID 34868034, 2021). "OGT was downregulated in ovarian cancer, which in turn, promotes cisplatin resistance by inducing autophagy." (PMID 30987661, 2019). "This destructive act by OGT against Nrf2 may be blocked (Point 11) by the action of miR-181d—an inhibitor of OGT found to target the 3’UTR of OGT mRNA to prevent OGT expression in ovarian cancer, elevating Nrf2 activation and providing cisplatin resistance." (PMID 36829925, 2023). "OGT downregulation can induce cisplatin resistance in ovarian cancer by promoting autophagy." (PMID 36647045, 2023). "To investigate the impact of OGT/OGA in ovarian cancer patients, we analyzed copy-number alterations of which from the cBioPortal for Cancer Genomics database and found that more up-regulation of OGT could be observed but not OGA." (PMID 35795059, 2022). "Finally, we found aberrant expression of OGT and OGA to be associated with ovarian cancer patient survival." (PMID 35795059, 2022). "Aneta Rogalska and colleagues found that abnormal OGT expression could induce ovarian cancer cell apoptosis." (PMID 35795059, 2022). "Additionally, OGT knock-down increases resistance to cisplatin of ovarian cancer cells and xenografted in mice." (PMID 36059648, 2022). "KEGG pathway analysis of OGT/OGA related pathways with ovarian cancer." (PMID 35795059, 2022). "However, similar to these findings in CLL, OGT and O-GlcNAcylated protein levels were significantly lower in ovarian cancers resistant to chemotherapy compared to chemosensitive cancers." (PMID 34868034, 2021). "Thus, we speculate that OGT can regulate KEAP1/NRF2 through glycosylation in ovarian cancer cells to regulate the cisplatin resistance of OC cells." (PMID 34876558, 2021). "Our results showed that high expression of OGT/OGA significantly impaired the PFS and PPS in ovarian cancer patients." (PMID 35795059, 2022). "In addition, increased OGA and OGT levels impaired PFS, and shortened PPS in ovarian cancer patients." (PMID 35795059, 2022). "Since significant alteration of OGT and OGA was observed in SKOV3 cells after KU60019 treatment, we next evaluated the prognostic value of these genes in ovarian cancer patients, including overall survival (OS), progression-free survival (PFS), and post-progression survival (PPS)." (PMID 35795059, 2022). "We further show that miR-542-5p might target OGT and OGA, suggesting miR-542-5p as a novel target for ovarian cancer therapy." (PMID 35795059, 2022). "Collectively, these results indicated that OGT and OGA could substantially influence the survival rate of ovarian cancer patients from several aspects." (PMID 35795059, 2022). "Here, we found that ATM inhibition could elevate the expression of OGT and OGA while significantly suppressing the level of miR-542-5p in ovarian cancer SKOV3 cells When miR-542-5p was overexpressed under ATM inhibition, OGT expression was effectively inhibited." (PMID 35795059, 2022).
breast tumor (9 papers, 2012 to 2025). "In the NVP-BEZ235-resistant MDA-MB-231 breast tumor cell line, loss of OGT expression resulted in increased sensitivity to NVP-BEZ235." (PMID 23029544, 2012). "Clinically, high expression of OGT, MORC2, SNAIL, and CTGF in breast tumors is associated with poor patient prognosis." (PMID 34974534, 2022). "Caldwell and co-workers demonstrated that mice injected with OGT knockdown breast tumor cells showed a fourfold reduction in tumor volume and mass when compared with injected control cells." (PMID 24918087, 2014). "There was also an association between O-GlcNAc, OGT, and OGA levels with breast tumor malignancy." (PMID 24918087, 2014). "Breast tumor cell lines overexpressing OGT considerably increased cell mobility." (PMID 24918087, 2014). "OGT may function as an oncogene, as it required for the survival of several breast tumor cell lines, and may regulate levels of p27Kip1 and FoxM1." (PMID 23029544, 2012). "In this study, we demonstrated that in an obese condition, elevated nutrient levels enhance HBP activity in breast tumor cells, thereby increasing the UDP‐GlcNAc pool and the activity of O‐GlcNAc transferase (OGT)." (PMID 39868848, 2025). "To determine the clinical relevance of our findings, we performed immunohistochemical (IHC) staining using a tissue microarray (TMA) containing 126 human breast tumor samples with an antibody against MORC2, O-GlcNAc, OGT, GFAT, SNAIL, or CTGF." (PMID 34974534, 2022). "Gene expression signatures of low OGT activity and high NRF2 activation are strongly correlated in several breast tumor datasets and OGT inhibition induces NRF2 and subsequently reduces cysteine-deprivation induced-oxidative stress in breast MDA-MB-231 cells." (PMID 36059648, 2022). "The treatment with OGT inhibitors of MCF-10A-ErbB2 and MDA-MB-231 breast tumor cells decreased the cell migration using Transwell assays." (PMID 24918087, 2014).
lung adenocarcinoma (9 papers, 2017 to 2024). A carcinoma that arises from the lung and is characterized by the presence of malignant glandular epithelial cells. "Our data suggest that O-GlcNAcylation sites in the N-terminal region are important for the function of SAM68 in regulating cancer cell migration and invasion and that concomitant high expression of SAM68 and OGT in lung adenocarcinoma tissues is associated with poor patient outcome." (PMID 35008409, 2022). "In this study, we examined 318 lung adenocarcinomas including two independent TMAs, one comprising of stage I cancers and the other tumors at various clinical stages, to evaluate associations between OGT, OGA, and cellular O-GlcNAcylation and both clinicopathological parameters and patient outcome." (PMID 30123425, 2018). "We previously found that OGT expression is an independent prognostic factor in patients with lung adenocarcinoma." (PMID 35008409, 2022). "Multivariate analysis revealed that high OGT was a prognostic factor for both RFS and OS, indicating OGT as a potential biomarker in early-stage lung adenocarcinoma." (PMID 34771527, 2021). "Our findings indicate OGT is a promising biomarker for further classifying early stage lung adenocarcinomas." (PMID 30123425, 2018). "In conclusion, this study demonstrated for the first time that OGT protein expression independently predicts poor outcome in patients with early stage lung adenocarcinoma." (PMID 30123425, 2018). "The expression level of OGT was statistically different between different histological subtypes of lung adenocarcinoma (P=0.028)." (PMID 30123425, 2018). "Our data indicate that high expression of OGT independently predicts poor survival outcomes of patients with stage I lung adenocarcinomas." (PMID 30123425, 2018). "An elevated OGT expression was observed in the majority of human lung adenocarcinoma tissues compared with normal lung tissues in 7 out of 8 analyzed datasets − one remaining dataset (Bhattachajee) revealed a remarkable decrease in MGEA5 expression." (PMID 28878262, 2017). "In addition, recent analyses of OGT and OGA expression using the Oncomine cancer microarray database found elevated OGT mRNA in lung adenocarcinoma tissues compared with normal lung tissues in most datasets." (PMID 30123425, 2018). "However, the mechanism responsible for OGT upregulation in lung adenocarcinoma remains to be determined." (PMID 30123425, 2018). "Our retrospective study suggested that OGT may be a promising prognostic biomarker in early stage lung adenocarcinomas." (PMID 30123425, 2018). "The expression of OGT in patients with stages II, III, and IV lung adenocarcinomas was higher than that in patients with stage I lung adenocarcinoma." (PMID 34771527, 2021). "We have previously revealed a positive correlation between OGT and OGA protein expression in lung adenocarcinoma tissues." (PMID 33801653, 2021). "When cultured CL1-5 or A549 human lung adenocarcinoma cells were treated with an OGA inhibitor, either Thiamet G (TMG) or PUGNAc, to elevate O-GlcNAcylation, the amount of OGT protein decreased while that of OGA increased." (PMID 33801653, 2021). "We used immunohistochemistry to explore the utility of OGT, OGA, and O-GlcNAc as potential biomarkers for lung adenocarcinoma." (PMID 30123425, 2018). "We also observed a positive correlation between OGT and OGA levels in lung adenocarcinoma, and high levels of both enzymes predicted poor patient outcomes." (PMID 30123425, 2018). "We assessed relationships between OGT, OGA, and O-GlcNAc levels in lung adenocarcinoma tissues using the Spearman rank correlation analysis." (PMID 30123425, 2018). "In this study, the expression of OGT, OGA, and O-GlcNAc were examined in lung adenocarcinoma tissues using immunohistochemistry, and the clinicopathological features as well as patients’ outcome were evaluated to assess the prognostic relevance of these markers." (PMID 30123425, 2018).
lung adenocarcinoma (continued). "Together, our data suggest that OGT expression may serve as an independent prognostic factor for RFS and OS in patients with early stage lung adenocarcinoma." (PMID 30123425, 2018). "Consistently, our findings that only OGT, but not OGA or O-GlcNAc level in tumors independently predicts survival implies that the key lever in tipping O-GlcNAcylation homeostasis of lung adenocarcinoma is OGT expression." (PMID 30123425, 2018).
neuroblastoma (9 papers, 2014 to 2025). Neuroblastoma (NB) is the most common solid, extracranial childhood tumor. "We used patient-derived induced pluripotent stem cells, a transgenic mouse model of AD, SH-SY5Y neuroblastoma cell lines to examine the effect of sustained O-GlcNAcase inhibition by Thiamet-G (TMG) or OGT deficiency on mitophagy using biochemical analyses." (PMID 39175808, 2024). "Overexpression of either OGT or OGA in SH-SY5Y neuroblastoma cells lowers mitochondrial respiration, disrupts morphology, and decreases the expression of respiratory chain and tricarboxylic acid cycle (TCA) proteins." (PMID 38192280, 2023). "In our current study, we show that disruptions to O-GlcNAc homeostasis by OGA inhibition, OGA KD, and OGT knock-down (KD) all increase ERK phosphorylation in SH-SY5Y neuroblastoma cells." (PMID 37469955, 2023). "Interestingly, the OGT inhibitor TMG appears to potentiate the ISR in neuroblastoma cells and in mouse brains." (PMID 41101503, 2025). "Moreover, OGT knockdown (KD) in SH-SY5Y neuroblastoma cells elevates ATF4 and ATF5 mRNA and protein expression." (PMID 38192280, 2023). "Intriguingly, MYPT1 is also a targeting subunit of OGT in neuroblastoma cells, raising the tantalizing possibilty that MYPT1 targets both PP1β and OGT to the same substrate, so that the substrate protein could be dephosphorylated and O-GlcNAcylated simultaneously." (PMID 30105004, 2018). "We did a serum reactivation time-course followed by western blot in SH-SY5Y neuroblastoma cells after long-term O-GlcNAcase (OGA) inhibition by Thiamet-G (TMG) treatment, O-GlcNAc transferase (OGT) knock-down (KD) and OGA KD." (PMID 37469955, 2023). "Furthermore, the effects of OGT inhibitors in autophagy were also examined in two different neuronal cell lines, human SH-SY5Y neuroblastoma and U87MG glioblastoma." (PMID 33317171, 2020). "For example, p38 MAPK affects O‐GlcNAcylation of neurofilament H in neuroblastoma cells by interacting with OGT and not affecting phosphorylation." (PMID 30515991, 2019).